INS (insulin)
Diseases named in the same sentence as INS in open-access papers (continued):
Sharing a sentence is not in itself a finding about the gene and the disease.
Hyperinsulinemia (continued). "Treatment with CNX-010-49 reduced hyperinsulinemia (both fasting and fed plasma insulin levels) and improved peripheral insulin sensitivity as evident from improved insulin tolerance test which was further supported by reduced glucose intolerance." (PMID 25098735, 2014). "Because a fasting plasma insulin level of 11μU ml−1 is reported to be one of the criteria for hyperinsulinemia in a study enrolling Japanese subjects, most of the subjects in the higher insulin group in this study were in a state of hyperinsulinemia." (PMID 25177913, 2014). "Recently, evidence has emerged on early-life stress-induced metabolic derangements, for example hyperinsulinemia and altered insulin sensitivity on exposure to a high energy diet later in life." (PMID 24860550, 2014). "HFD-fed hamsters were insulin resistant as reflected by hyperinsulinemia as well as significantly increased HOMA-IR values." (PMID 25136608, 2014). "Another clinical study found that the change in the tHcy level during hyperinsulinemia is correlated with insulin sensitivity." (PMID 25401978, 2014). "Increased serum ferritin concentrations and excessive iron can contribute to hyperinsulinemia and reduced insulin function." (PMID 24764731, 2014). "In the group of diabetic patients with hyperinsulinemia, the amino acid levels were significantly increased, which generally demonstrated good concordance with insulin-related markers and adiponectin levels." (PMID 25177913, 2014). "Impaired changes in metabolic parameters of insulin and diet-induced obesity were also attenuated with exercise, reversing maternal separation-induced hyperinsulinemia and increased body weight relative to HFD controls and stressed sedentary counterparts." (PMID 24860550, 2014). "In IR, even when pancreatic β cells show a good function, compensatory hyperinsulinemia occurs and promotes insulin-induced proliferation of VSMCs via the SHC/Raf/MAPK pathway; in these conditions, hyperinsulinemia accelerates arterial atherosclerosis." (PMID 24604418, 2014). "In this regard, GC-induced IR has been found to enhance β-cell function and mass, inducing hyperinsulinemia as a compensatory response to the increased insulin needs imposed by IR." (PMID 24705399, 2014). "Peripheral hyperinsulinemia is the combined result of insulin hypersecretion and reduced insulin clearance." (PMID 24524730, 2014). "The slow rise and fall in MSNA produced by hyperinsulinemia would be explained by the time insulin needs to cross the blood brain barrier." (PMID 25400585, 2014). "Significant hyperinsulinemia in fa/fa rats was represented by extreme insulin levels that reached 12-fold (p < 0.001) at 12 weeks of age and 9-fold at 33 weeks of age (p < 0.001) in lean age-matched controls." (PMID 25257559, 2014). "Since ZDF rats had ∼14 fold higher plasma insulin compared to ZL rats, at 11-weeks they had compensative hyperinsulinemia." (PMID 25062042, 2014). "Clinical studies have demonstrated that men and women with hyperprolactinemia have postprandial hyperinsulinemia and an exaggerated insulin secretory response to glucose and arginine." (PMID 25126749, 2014). "Correlation of fetal insulin with fetal leptin levels suggests that fetal hyperinsulinemia, by stimulating white adipose tissue growth, the main leptin source, leads to higher leptin production in fetal adipose tissue." (PMID 25258707, 2014). "Once the fetal pancreas commences to produce and secrete insulin in the late first trimester, fetal hyperglycaemia leads to fetal hyperinsulinemia and both stimulate fetal metabolism." (PMID 25258707, 2014). "IR is followed by compensatory hyperinsulinemia, which promotes insulin-induced proliferation of VSMCs via the SHC/Raf/MAPK pathway, and accelerates artery atherosclerosis." (PMID 24604418, 2014). "Basal hyperinsulinemia in DEX-treated rodents can also be explained by the increased β-cell mass which is usually observed in insulin-resistant rodents fed a high-fat or high sucrose diet." (PMID 25313308, 2014).
Hyperinsulinemia (continued). "Proposed mechanisms of hyperinsulinemia have been reported by several authors, including increased insulin secretion by the pancreas, diminished hepatic insulin extraction, or a combination of the two." (PMID 24397589, 2014). "It is generally believed that the control of hyperinsulinemia is a result of improved insulin sensitivity in the peripheral tissues." (PMID 24740421, 2014). "According to the data, in the insulin-resistant state the overstimulation of mitogen-activated protein kinase (MAPK)-dependent pathways by compensatory hyperinsulinemia in the endothelium resulted in an increased expression of E-selectin." (PMID 23934358, 2014). "Although plasma insulin level in control group increased from Day −2 to Day 28 by about 4.5-fold, tofogliflozin administration prevented this hyperinsulinemia." (PMID 25000147, 2014). "The role of insulin clearance is less investigated in the pathogenesis of hyperinsulinemia relative to insulin secretion in the obese models." (PMID 24740421, 2014). "Insulin production and secretion appeared to be inhibited, suppressing the developing hyperinsulinemia present in untreated controls." (PMID 25473963, 2014). "In this study, combined therapy can decrease hyperinsulinemia stress, which improves insulin activity evaluated by the HOMA index via reducing plasma FFA levels." (PMID 25024728, 2014). "According to previous cross-sectional studies, insulin sensitivity was associated with circulating BDNF, and hyperinsulinemia was a risk factor for depression." (PMID 24524285, 2014). "Altogether, these data provide evidence for a role of pre-receptor glucocorticoid metabolism in insulin secretion under basal physiological conditions that supports insulin hypersecretion and fasting hyperinsulinemia." (PMID 24705399, 2014). "In parts of the body responding normally to insulin, the hyperinsulinism of insulin resistance likely is construed as a state of insulin excess." (PMID 25486190, 2014). "Analysis of basal hormone levels showed normal thyroid function and adrenal function but considerable basal hyperinsulinism (the insulin levels were 54.5 and 49.2 μU/ml, respectively)." (PMID 24479866, 2014). "Retrospective analyses of plasma samples detected normal insulin levels at 3–4 years of age, followed by hyperinsulinemia and a progressive decline in plasma insulin levels." (PMID 23647575, 2013). "Failure to suppress FFA is associated with inhibition of carbohydrate oxidation and glycogen synthesis in muscle during hyperinsulinemia, reduced clearance of insulin by the liver, and elevated VLDL-triglyceride production." (PMID 23434905, 2013). "This leads to the typical hyperinsulinemia observed in insulin-resistant states and in nonalcoholic fatty liver disease (NAFLD)." (PMID 23509418, 2013). "HFD-fed hamster was insulin resistant reflected by hyperinsulinemia as well as significantly increased value of HOME-IR." (PMID 24223615, 2013). "We previously generated mice lacking leptin signaling in β-cells by using the Cre-loxP strategy and showed that these animals develop increased body weight and adiposity, hyperinsulinemia, impaired glucose-stimulated insulin secretion and insulin resistance." (PMID 23936486, 2013). "Rather, hyperinsulinemia seems to play an important role in the pathogenesis of these conditions, since plasma insulin levels were almost the same between the WT mice and Gck+/− mice fed a HF diet." (PMID 24284392, 2013). "Circulating ET-1 concentrations rapidly elevate with hyperinsulinemia though there is a paucity of evidence for ET-1 signaling, in vivo, beyond 2 h post insulin stimulation and human prepro-ET-1 mRNA is labile with an intracellular half-life of ∼15 min." (PMID 24303186, 2013). "Many reports have demonstrated that consumption of high-sucrose diet induces impaired glucose tolerance and hyperinsulinemia, and decreases insulin sensitivity." (PMID 23497124, 2013).
Hyperinsulinemia (continued). "The present study investigated the effect of maintaining hyperinsulinemia during HD by either glucose or glucose-insulin infusion on serum bioactive IGF-I and plasma IL-6." (PMID 23557110, 2013). "In the presence of euglycemic hyperinsulinemia, insulin secretory rates with exenatide were significantly (3.5-fold) higher than with PBO." (PMID 23256660, 2013). "The role of insulin in TPP was revealed by the finding that hyperinsulinemia was observed during acute attacks of TPP and that TPP patients had exaggerated insulin responses to oral glucose challenge in comparison with patients with pure hyperthyroidism." (PMID 23939916, 2013). "Hyperinsulinemia is a compensatory response for increasing insulin resistance of liver, muscles, and adipose tissue." (PMID 23476808, 2013). "Lower glucose absorption increases insulin production by the pancreas to keep glucose levels normal, thus hyperinsulinemia is frequent in IR." (PMID 24084729, 2013). "As a consequence, a balancing mechanism stimulates insulin release resulting in a chronic compensatory hyperinsulinemia." (PMID 23497533, 2013). "Accompanying insulin levels were also elevated which is similar to the hyperinsulinemia seen in human DM2 as a result of impaired peripheral insulin metabolism." (PMID 24324455, 2013). "The main strengths of our study include thorough patient examinations with gold standard methods for measurement of insulin sensitivity, and using two steps of hyperinsulinemia." (PMID 24148878, 2013). "The indirect effects of hyperinsulinemia on carcinogenesis are attributable to the action of insulin on circulating endogenous growth factors together with their binding proteins." (PMID 24073332, 2013). "The increase in plasma insulin levels was time-dependent in both the high energy diet groups of rats and the hyperinsulinemia was maintained linearly until the termination of the experiment." (PMID 23451227, 2013). "In particular, metformin, the drug of choice for the management of DM2, reduces levels of both circulating glucose and insulin in patients with insulin resistance and hyperinsulinemia." (PMID 23936520, 2013). "In the female rats, hyperinsulinemia was shown from 4 to 12 weeks of age, and the insulin levels decreased gradually." (PMID 23691524, 2013). "Hyperphagia, particularly pronounced under high-energy/high-fat dietary provocation, was accompanied with hyperleptinemia, hyperinsulinemia, increased insulin-glucose-ratio, and correlated with body fat." (PMID 24265718, 2013). "In the obese state, an increase in adipose tissue mass leads to increased secretion of insulin and leptin into the circulation resulting in the development of hyperinsulinemia and hyperleptinemia, respectively." (PMID 23590862, 2013). "At this time, the insulin secretion of pancreatic beta cell depletes and the hyperinsulinemia recedes, the mouse exhibits ketosis, gradual body weight loss, and deceases no longer than 8 to 10 months." (PMID 23671868, 2013). "Since HFD induces non-alcoholic fatty liver and causes hyperinsulinemia in mice, a remarkable observation is that after 16 weeks on HFD, Eng+/− mice showed decreased hepatic triglyceride content and lower insulin levels compared with WT mice." (PMID 23336009, 2013). "This decline, therefore, contributes approximately 50% to the overall development of hyperinsulinemia, the remainder of the increase being related to β-cell hypersecretion of insulin." (PMID 23886319, 2013). "There was no significant change on fasting blood glucose or glucose tolerance between control and DC260126 treat Zucker fatty rats, only the insulin sensitivity was improved and the hyperinsulinemia was reduced." (PMID 23776696, 2013). "One contributor to reduced insulin signaling is a downregulation of insulin receptor expression induced by hyperinsulinemia." (PMID 24252636, 2013).
Hyperinsulinemia (continued). "The male SDT fatty rats showed hyperinsulinemia from 4 to 8 weeks of age, but after 16 weeks their insulin levels decreased to levels similar to those in SDT rats." (PMID 23691524, 2013). "Insulin-mediated glucose disposal is essentially impaired in most identified cases, as glucose levels are the main feedback signal for compensatory hyperinsulinemia." (PMID 24324517, 2013). "In addition, hyperinsulinemia reflects some degree of causality in carcinogenesis, while risk of cancer may be expected rather to diminish with long-term type II DM since levels of endogenous insulin fall down due to beta cells failure." (PMID 23476808, 2013). "Strikingly, JNK-1KO mice were also protected from HFD-induced hyperinsulinemia as indicated by reduced circulating levels of insulin in comparison to WT mice." (PMID 23349837, 2013). "Overall, previous data obtained in humans and our current findings in rodents indicate that Eng seem to play an important role in the control of insulin levels, and heterozygous deficiency of Eng decreases HFD-induced hyperinsulinemia." (PMID 23336009, 2013). "As recently shown, obese ZDF rats are insulin-resistant and have basal hyperinsulinemia that is due mainly to hypersecretion of insulin, as indicated by their elevated basal C-peptide levels." (PMID 22621761, 2012). "Instead, the very early stages of glucose dysregulation, such as low insulin sensitivity and compensatory chronic hyperinsulinemia seem to play a role." (PMID 23251434, 2012). "GPR26 deficiency significantly increased serum insulin level in both female and male GPR26−/− mice, suggesting hyperinsulinemia in GPR26 knockout mice." (PMID 22815809, 2012). "Increased iron stores further deteriorate hyperinsulinemia through hepatic dysfunction, decreased capacity for hepatic insulin extraction, and the insulin metabolism." (PMID 22848554, 2012). "Following the initiation of insulin substitution therapy in these patients, they can have hypo-, normo- or even hyperinsulinemia depending on the dose of injected or infused insulin." (PMID 22262970, 2012). "In opposition to the LPS study findings, a 6 h insulin infusion that induced acute, supraphysiological hyperinsulinemia also increased skeletal muscle IL-1β about 1.75 fold above baseline measurements." (PMID 26486919, 2012). "In comparison to normal subjects, oral doses of leucine (0,2 g/kg) stimulated exaggerated insulin release and induced basal hyperinsulinemia in obese patients." (PMID 22891897, 2012). "Elevated plasma glucose is sensed by pancreatic beta cells, which increase insulin secretion to compensate for hyperglycemia, resulting in circulating hyperinsulinemia." (PMID 22804097, 2012). "In the obese state, an increase in adipose tissue mass leads to increased secretion of insulin and leptin into the circulation, often resulting in the development of hyperinsulinemia and hyperleptinemia, respectively." (PMID 21904565, 2012). "As a consequence we observed higher ANGPTL4 expression in the insulin-resistant compared to the insulin-sensitive group after 6 hours of hyperinsulinemia." (PMID 22471940, 2012). "Low cognitive scores are seen in middle aged individuals with hyperinsulinemia, low insulin sensitivity, beta-cell function and low aerobic capacity." (PMID 23251434, 2012). "Greenhaff and colleagues have recently reported AKT (PKB) mRNA abundance remains unchanged following three hours of hyperinsulinemia under four different steady-state insulin concentrations range from 5 mU/l to ∼170 mU/L." (PMID 22396763, 2012). "SREBP1 expression is reduced in human adipocytes and skeletal muscle in obese and insulin resistant people but can be returned to normal by hyperinsulinemia." (PMID 22719926, 2012). "The most striking difference in gene expression of the insulin-resistant group during hyperinsulinemia was reduced transcription of genes involved in mitochondrial respiration (mitochondrial respiratory chain, GO:0001934)." (PMID 22471940, 2012).
Hyperinsulinemia (continued). "During euglycemic hyperinsulinemia, the insulin independent glucose transporter GLUT1 is a major mediator of basal cardiac glucose uptake." (PMID 22963383, 2012). "Subcutaneous adipose tissue biopsies were obtained before and after 3 and 6 hours of intravenously maintained euglycemic hyperinsulinemia from 9 insulin-resistant and 11 insulin-sensitive females." (PMID 22471940, 2012). "In both in vitro and in vivo experiments, insulin-mediated TG accumulation in the liver exhibited a bimodal function, where both hypo and hyperinsulinemia led to augmented liver fat storage." (PMID 22745692, 2012). "Hyperinsulinemia is severe enough that secondary adipose insulin resistance occurs, as evidenced by an increased rate of basal lipolysis." (PMID 22442717, 2012). "Dietary fiber-rich meals with a low glycemic index, a lower content of simple carbohydrates, and more exercise, as well as α-glucosidase inhibitor (α-GI) or insulin with α-GI treatment, improve hyperinsulinemia and hyperglycemia in LC patients." (PMID 23197979, 2012). "The most prominent difference in gene expression of the insulin-resistant group during hyperinsulinemia was reduced transcription of nuclear genes involved in mitochondrial respiration (mitochondrial respiratory chain, GO:0001934)." (PMID 22471940, 2012). "Despite the hyperinsulinemia in Tg mice, rmuFGF21 was ineffective in improving plasma insulin and glucose tolerance." (PMID 22792234, 2012). "Using a more direct approach, hyperinsulinemia, achieved through a six-h insulin infusion, increased circulating TNF and IL-6 concentrations in non-obese mares." (PMID 26486919, 2012). "It is nutritionally important that improving hyperinsulinemia brings about normalization of insulin-dependent glucose uptake and glycogen synthesis." (PMID 23197979, 2012). "This transcript was elevated during hyperinsulinemia in the insulin-resistant as compared to the insulin-sensitive group." (PMID 22471940, 2012). "T2D is characterized by a peripheral resistance to the action of insulin and a rise in insulin production by β cells in a process called “compensatory hyperinsulinemia” to force glucose uptake in peripheral tissues." (PMID 23326021, 2012). "Hyperinsulinemia is one of the most frequent endocrine features in overweight people which results in insulin desensitization." (PMID 22654904, 2012). "In individuals with IR or hyperinsulinemia the production of nitric oxide is decreased but the stimulatory effect of insulin in ET-1 is preserved leading to vasoconstriction and hypertension." (PMID 22682151, 2012). "Lack of a significant difference in IAUC of BG between MetS+ and MetS− patients in front of significantly greater IAUC of insulin suggests that hyperinsulinemia was sufficient to buffer in MetS+ patients the glycemic response to the meal." (PMID 22474578, 2012). "Reduced mRNA expression of mitochondrial pathways was a predominant phenotype in the insulin-resistant group during hyperinsulinemia." (PMID 22471940, 2012). "In type 2 diabetic patients, co-treatment with rhIGF-I can significantly reduce glucose levels and insulin requirement while improving glucose tolerance, hyperinsulinemia, and hypertriglyceridemia." (PMID 23148873, 2012). "External supplementation of recombinant murine leptin ameliorate CLA-induced hepatic steatosis and hyperinsulinemia by decreasing hepatic lipogenesis and increasing insulin sensitivity respectively." (PMID 21869929, 2012). "In the present study we made a novel observation of ELOVL6 down-regulation in the obese insulin resistant as compared to the lean insulin-sensitive group in hyperinsulinemia." (PMID 22471940, 2012). "Inflammatory pathways with complement components (inflammatory response, GO:0006954) and cytokines (chemotaxis, GO:0042330) were strongly up-regulated in insulin-resistant as compared to insulin-sensitive subjects both before and during hyperinsulinemia." (PMID 22471940, 2012).